SNTB1 (syntrophin beta 1)
Description:
Adapter protein that binds to and probably organizes the subcellular localization of a variety of membrane proteins. May link various receptors to the actin cytoskeleton and the dystrophin glycoprotein complex.
Synonyms: DAPA1B; TIP-43; SNT2B1; 59-DAP; A1B; BSYN2; SNT2
Tractability: Antibody: its Gene Ontology location is reachable by antibodies, with high confidence; UniProt places it where antibodies can reach, with medium confidence. PROTAC: ubiquitination databases record sites on it; its protein half-life has been measured.
Gene: Protein-coding gene on chromosome 8 (120,535,745 to 120,813,273, reverse strand). Ensembl gene ENSG00000172164.
Subcellular location: Cell membrane, sarcolemma; Cell junction; Cytoplasm, cytoskeleton
Pathways (Reactome):
Extracellular matrix organization: Formation of the dystrophin-glycoprotein complex (DGC)
Gene Ontology:
Molecular function: protein binding; PDZ domain binding; structural molecule activity
Biological process: camera-type eye development; muscle contraction
Cellular component: focal adhesion; protein-containing complex; dystrophin-associated glycoprotein complex; neuromuscular junction; plasma membrane; synapse; anchoring junction; cytoskeleton; sarcolemma
Genetic constraint (gnomAD): Loss-of-function variants: 34 observed, 45.85 expected, observed/expected ratio (o/e) 0.74, 90% interval 0.56 to 0.99. The upper end of that interval is the gene's LOEUF score, 0.99, which puts it in group 4 of 6, group 1 being the genes least tolerant of losing a copy. Missense variants: 782 observed, 705.74 expected, observed/expected ratio (o/e) 1.11, 90% interval 1.04 to 1.17. Synonymous variants: 299 observed, 290.57 expected, observed/expected ratio (o/e) 1.03, 90% interval 0.94 to 1.13.
Homologues: Orthologues: chimpanzee SNTB1 (99% identical), macaque SNTB1 (99% identical), pig SNTB1 (96% identical), rabbit SNTB1 (95% identical), dog SNTB1 (93% identical), mouse Sntb1 (93% identical), rat Sntb1 (92% identical), guinea pig SNTB1 (87% identical), tropical clawed frog sntb1 (72% identical), zebrafish sntb1 (65% identical), Drosophila melanogaster Syn1 (43% identical), Caenorhabditis elegans stn-1 (35% identical). Paralogues in human: SNTB2 (54% identical), SNTA1 (47% identical), SNTG2 (25% identical), SNTG1 (22% identical).
Diseases named in the same sentence as SNTB1 in open-access papers:
SNTB1 is named in the same sentence as 14 diseases in open-access papers, as found by Europe PMC text mining. Sharing a sentence is not in itself a finding about the gene and the disease. The quoted sentences say what the papers report.
colorectal cancer (3 papers, 2021 to 2025). A primary or metastatic malignant neoplasm that affects the colon or rectum. "SNTB1 has been reported in the field of cancer as a promoter of colorectal cancer progression through activation of the ERK and AKT signaling pathways." (PMID 40774945, 2025). "SNTB1 has recently been shown to regulate colorectal cancer progression and stemness through the Wnt/β-catenin signaling pathway." (PMID 38240752, 2024).
myopia (2 papers, 2021 to 2024). "In the current study, our GWAS analysis revealed SNTB1 as the gene most significantly associated with high myopia." (PMID 39062192, 2024). "Recent studies revealed that the functional variants of SNTB1 correlated with several diseases, including acute pancreatitis, oral cancer, lung cancer, and severe myopia." (PMID 34663329, 2021). "In addition, it has also been reported that SNTB1 is closely related to the occurrence of oral cancer and is considered to be a susceptibility locus for severe myopia." (PMID 34663329, 2021).
colon cancer (1 paper, 2025). "Previous studies have confirmed that YAP1 may partially reverse the inhibitory effect of SNTB1 knockdown on the phenotype of CRC cells and the Wnt/β‐catenin/MYC signaling pathway, thereby affecting the invasiveness of colon cancer cells and the growth and metastasis of tumors in vivo." (PMID 41152153, 2025).
lung adenocarcinoma (1 paper, 2021). A carcinoma that arises from the lung and is characterized by the presence of malignant glandular epithelial cells. "Moreover, lower SNTB1 expression correlated with shorter survival rate in lung adenocarcinoma patients, while SNTB1 over-expression associated with shorter survival of CRC patients." (PMID 34663329, 2021).
muscular dystrophies (1 paper, 2013). "The product of SNTB1, β1-syntrophin, has been implicated in both muscular dystrophies and cholesterol homeostatis." (PMID 24130694, 2013).
Stroke (1 paper, 2020). Sudden impairment of blood flow to a part of the brain due to occlusion or rupture of an artery to the brain. "Three genes (HGF, SNTB1, and SERPINC1 [MIM: 107300]) were found in the “stroke” group but not in the “long survivor” group." (PMID 32898326, 2020).
tumor (5 papers, 2020 to 2025). "The results indicated that ZC3H13 overexpression promoted the proliferation of GC in vivo, with tumor volume and weight significantly higher than that of the control group, but these effects were reversed by SNTB1 knockdown." (PMID 40774945, 2025). "By evaluating tumor volume, intratumoral green fluorescent protein (GFP) fluorescence, tumor size, and tumor weight, we found that SNTB1 knockdown significantly suppressed tumor growth of both HCT116 and RKO cells in vivo." (PMID 34663329, 2021). "Importantly, SNTB1 promotes tumor growth and progression of CRC, possibly by reducing the expression of PKN2 and activating the ERK and AKT signaling pathway." (PMID 34663329, 2021). "CDCA7, CELSR3, PACS1, SNTB1, and TBC1D31 showed consistent upregulation in CRC tumor samples and pre-surgical cfRNA, while GFI1B, HPGD, SH3BGRL2, SIAE, PKHD1L1, and TDP2 showed downregulation in CRC tumor samples and pre-surgical cfRNA." (PMID 37091184, 2023).
SNTB1 also shares sentences with these, for which no sentence is quoted: cancer (2 papers); breast carcinoma (1); gastric cancer (1); oral cancer (1); ovarian carcinoma (1); prostate carcinoma (1); schizophrenia (1).